CD1D (CD1d molecule)
Diseases named in the same sentence as CD1D in open-access papers (continued):
Sharing a sentence is not in itself a finding about the gene and the disease.
tumor (continued). "Surface expression of CD1d on tumor cells is assumed to directly correlate with NKT cell-mediated cytotoxicity." (PMID 29018445, 2017). "Second, when loaded with αGalCer, these CD1d-antitumor fusion proteins will specifically activate Type 1 iNKT cells and redirect both the innate and the adaptive antitumor responses to the tumor site, in view of the transactivating properties of iNKT cells." (PMID 29163493, 2017). "In order to redirect iNKT cell immunity at the tumor site, we have developed CD1d molecules genetically fused to an antibody scFv fragment specific of the HER2 or CEA antigens, which are overexpressed in several cancers." (PMID 29163493, 2017). "While these findings illustrate the importance of CD1d in mounting iNKT-driven antitumor immune responses, there exists at least one example where increased CD1d expression and tumor progression are positively correlated." (PMID 29326711, 2017). "In vivo such an upregulation would be disadvantageous for the tumor cells, as any cells in which CD1D upregulation occurs would be targeted by invariant-NKT cells, a selection pressure which is no longer present in vitro." (PMID 28931069, 2017). "Treatment with a CD1d-specific mAb has shown to protect mice from tumor metastasis by several groups." (PMID 29354122, 2017). "In vitro observations demonstrated that tumor cells expressing CD1d were more prone to lysis induced by NKT cells." (PMID 26895468, 2016). "The down-regulated genes included the following: 1) immune system activators such as CD14 and CD1d; 2) hematopoietic tumor suppressor IRF822; and 3) ZFP36L1, a promotor of monocyte/macrophage differentiation that represses CDK623." (PMID 27686215, 2016). "Proof that tumor immunosurveillance by type I NKT cells occurs through CD1d became clear when adoptive transfer of liver DN type I NKT cells from WT into CD1d KO mice (lacking all NKT cells) did not confer protection." (PMID 26895468, 2016). "The importance of OVA-specific CTLs among tumor infiltrating lymphocytes was suggested by a two-fold increase of OVA-specific CD8 T cells when the OVA/CpG-ODN vaccine was combined with the CD1d-therapy compared to the vaccine alone." (PMID 25426294, 2014). "Consistent with our previous work, the present results confirmed the accumulation of both innate and adaptive effector subsets in the tumor tissue when targeted with the combined vaccine and CD1d-anti-HER2 fusion protein therapy." (PMID 25426294, 2014). "Many hematologic malignancies express CD1d molecules and co-stimulatory proteins needed to induce anti-tumor immunity by NKT cells, yet most tumors are poorly immunogenic." (PMID 24955247, 2014). "To understand the mechanisms of immune regulation by iNKT cells we examined DC, which are largely CD1d+, and are the APCs required for cross-presentation of tumor antigens to T cells." (PMID 25349699, 2014). "In conclusion, combined vaccine/CD1d immunotherapy enhances the activation and recruitment of tumor-specific CD8 T cells, which appears to be favored by the local inflammation induced by activated iNKT and NK cell accumulation at the tumor site." (PMID 25426294, 2014). "The effects of antibody-mediated blockade of CD1d on DC number and phenotype, priming of anti-tumor T cells, and tumor response to treatment with local radiotherapy and anti-CTLA-4 antibody were evaluated." (PMID 25349699, 2014). "Firstly, combining the CD1d-antitumor therapy with tumor vaccines allows the prolonged reactivity of iNKT cells to multiple injections of αGC-loaded CD1d fusion proteins thus sustaining the anti-tumor immune response." (PMID 25426294, 2014). "In the present study, we aimed to combine a CpG-based peptide vaccine with the activation and tumor targeting of iNKT cells via the CD1d-anti-HER2 fusion protein." (PMID 25426294, 2014). "DC numbers and tumor-specific CD8+ T cell responses were at least partially restored by blocking CD1d, resulting in improved response to immunotherapy." (PMID 25349699, 2014).
tumor (continued). "Invariant natural killer T (iNKT) cells are CD1d-restricted T cells, which respond rapidly to antigen recognition and promote development of anti-tumor immunity in many tumor models." (PMID 25349699, 2014). "This highlights the advantage of combining a CD8 T cell vaccine with CD1d-fusion protein, which harnesses the innate immune response to boost the adaptive response and enhance anti-tumor immunity." (PMID 25426294, 2014). "The immunosuppressive effect seemed mediated by the sulfatide-reactive subset of type II NKT cells, as sulfatide treatment enhanced tumor growth in a CD1d-dependent manner." (PMID 25389427, 2014). "In this context, we have developed CD1d-antitumor fusion proteins consisting of the soluble part of the CD1d molecule fused to a scFv antibody fragment specific for the tumor antigens CEA or HER2." (PMID 25426294, 2014). "An induced fit antigen with enhanced binding to CD1d, naphthylurea (NU)-α-GalCer, heightened Th1 biased cytokine skewing, and conferred better tumor protection than α-GalCer." (PMID 25389427, 2014). "Tumor rejection was shown to be CD8+ T cell-dependent, and CD1d KO mice that rejected the tumor had significantly higher numbers of tumor infiltrating lymphocytes." (PMID 25389427, 2014). "The activation of iNKT cells by tumor-targeted CD1d molecules was also evidenced by their cytokine content." (PMID 23242316, 2013). "In the model experiment, we used OVA mRNA as an artificial tumor antigen together with α-GalCer/CD1d to induce the NKT cell-mediated adjuvant effects in vivo in situ." (PMID 24348476, 2013). "Instead, tumour specimens of patients with relapse-free survival showed a higher percentage of CD1d + cells." (PMID 23758773, 2013). "The requirement for CD1d tumor targeting to provide sustained reactivity of iNKT despite PD-1 up-regulation was further characterized." (PMID 23242316, 2013). "The importance of CD1d tumor targeting to promote sustained activation of iNKT cells and prolonged tumor inhibition is further characterized in mice in therapeutic settings." (PMID 23242316, 2013). "This prolonged responsiveness of iNKT cells resulted in potent antitumor activity when CD1d was targeted to the tumor site by its fusion to an anti-HER2 antitumor antibody fragment." (PMID 23242316, 2013). "Altogether, these results demonstrate the importance of targeting CD1d to the tumor site to favor a strong and prolonged reactivity of iNKT cells." (PMID 23242316, 2013). "The second attractive characteristic of our immunotherapy strategy is the targeting of recombinant CD1d fusion proteins to tumors by fusion of the extracellular part of CD1d to an antibody scFv fragment specific for a tumor antigen." (PMID 23242316, 2013). "The requirement of tumor-targeted CD1d treatment to achieve a therapeutic effect was best demonstrated in the mice treated with the irrelevant αGC/sCD1d-anti-HER2 fusion protein, as all animals had fast tumor growth." (PMID 23242316, 2013). "The importance of CD1d tumor targeting was confirmed in tumor-bearing mice in which only the specific tumor-targeted CD1d fusion protein resulted in tumor inhibition of well-established aggressive tumor grafts." (PMID 23242316, 2013). "Although surface CD1d expression of 4T1 tumor cells in vitro was negligible, in vivo tumors can express CD1d albeit at low levels (K. A. Pilones and S. Demaria unpublished data)." (PMID 23118781, 2012). "Alternatively, iNKT cells are also able to recognize α-GalCer loaded on CD1d-expressing tumor cells and mount an antitumor response that inhibited experimental metastases and rejected subcutaneous challenge of tumor cells." (PMID 23118781, 2012). "Effector CD8+ T cells were obtained from mice immunized with α-GalCer-loaded tumor extracts and adoptively transferred into recipient CD1d+/− mice." (PMID 23118781, 2012).
tumor (continued). "The importance of CD1d expression by tumor was further validated by shRNA knockdown of CD1d, which also demonstrated significantly increased tumor metastasis to lung." (PMID 21695190, 2011). "In summary, these data point to a correlation between downregulated CD1d expression by tumor and suppression of iNKT-regulated antitumor immunity in vivo." (PMID 21695190, 2011). "As assessed by histology, tumors in mice treated with the anti-CD1d antibody exhibited increased ability to metastasize to lung, with significantly increased numbers of tumor foci per lung (P = 0.0049)." (PMID 21695190, 2011). "Previous studies by the Smyth group reported potent tumor inhibition by administering an anti-CD1d blocking antibody in mice bearing multiple types of CD1d-deficient tumors, presumably by blocking the suppressive functions of type II NKT cells." (PMID 21695190, 2011). "Several studies have demonstrated a direct role for CD1d-expressing tumor cells in activating iNKT-mediated antitumor immunity." (PMID 21695190, 2011). "The ability of the anti-CD1d antibody to block tumor cytolysis was concentration-dependent, as compared to isotype control." (PMID 21695190, 2011). "Clearly, both tumor and systemic expression of CD1d are important for preventing metastasis of TM40D tumors." (PMID 21695190, 2011). "This was suggested to be due to the ability of CD1d-expressing tumor cells to recruit suppressive type II NKT cells in the absence of type I NKT cells." (PMID 21695190, 2011). "Several tumor types have been shown to express CD1d, and tumor expression of CD1d has been directly correlated with the ability of iNKT cells to induce direct tumor cytolysis in vitro and promote iNKT-mediated tumor immunity in vivo." (PMID 21695190, 2011). "The results of this study emphasize the importance of determining the CD1d expression status of the tumor when tailoring NKT-based immunotherapies for the prevention and treatment of metastatic breast cancer." (PMID 21695190, 2011). "In order to assess potential effects of downregulated CD1d expression by tumor on innate and adaptive antitumor immunity, we assessed spleens from tumor-implanted mice for levels of iNKT, NK, CD4+ and CD8+ T cells by FACS." (PMID 21695190, 2011). "At the point at which tumors were palpable (day 10 post tumor implantation), mice were injected intraperitoneally (i.p) with either anti-CD1d (3C11) blocking antibody, or vehicle control." (PMID 21695190, 2011). "Nevertheless, it should be taken into consideration that in the absence of strong exogenous ligands such as αGalCer, iNKT exhibit little cytotoxic activity against CD1d+ mouse and human tumor cells." (PMID 20072624, 2010). "Studies performed in vitro have shown that human iNKT can be directly cytotoxic against CD1d+ tumor cell targets." (PMID 20072624, 2010). "In a model of tumor recurrence the CD8+ T cell-mediated immunosurveillance was suppressed by IL-13 producing CD1d-restricted CD4+ T cells." (PMID 19968878, 2009). "BMDCs primed with iGb3 protected against tumor development and metastasis and this effect depended on CD1d-restricted iNKTs." (PMID 19968878, 2009). "Distinct tumor-infiltrating and tumor-resident cells express CD1d." (PMID 39941775, 2025). "Moreover, the ability to maintain CD1d expression on tumor cells, which is crucial for iNKT cell recognition, will be essential for studying their therapeutic potential." (PMID 39941775, 2025). "Notably, tumor-specific T cell receptor–engineered (TCR-engineered) CD1d-restricted iNKT cells induced robust antitumor responses by simultaneously targeting cancer cells and MDSCs in B16-Ova or MC38-Ova tumor-bearing mice." (PMID 40231459, 2025). "CD1d-restricted iNKT cells can directly kill CD1d+ tumor cells through CD1d recognition." (PMID 40231459, 2025).
tumor (continued). "Leveraging their inherent capacity for dual-targeting synergy—simultaneous engagement of protein antigens via CAR and CD1d-presented lipid antigens via their invariant TCR—coupled with robust tumor microenvironment (TME) remodeling, iNKT cells effectively overcome barriers in solid tumor therapy." (PMID 40698085, 2025). "A key advantage of NKT cells over conventional T cells may be their remarkable intrinsic anti-tumor activity, which is activated by glycolipids presented by CD1d on antigen-presenting cells through their endogenous T cell receptors (TCRs)." (PMID 39995672, 2025). "In addition, invariant NK T (iNKT) cells, CD1d-restricted lipid-specific T lymphocytes, enable the coordination of innate and acquired immunity and act as tumor immune surveillance." (PMID 40297580, 2025). "In fact, by targeting immune-suppressive myeloid cells via CD1d, recruiting cytotoxic T and NK cells, and activating APCs, iNKTs can create the conditions necessary for tumor eradication in solid malignancies and lymphoproliferative solid-like neoplasms." (PMID 41000376, 2025). "For example, upregulating CD1d expression on tumor cells could improve iNKT cell recognition and cytotoxicity." (PMID 39941775, 2025). "Critically, the intrinsic ability of iNKT cells to recognize CD1d-presented endogenous tumor lipids via their invariant TCR creates a dual-targeting synergy: this not only amplifies CAR-mediated cytotoxicity but also mitigates antigen escape by engaging lipid-specific killing pathways." (PMID 40698085, 2025). "Tumor-associated macrophages and myeloid-derived suppressor cells (MDSCs), two major components of the immunosuppressive TME54, both express high levels of CD1d, making them direct targets of NKT cells." (PMID 38744947, 2025). "The decreased expression of CD1d in IMPC may enable tumor cells to evade immune system regulation and enhance the metastatic potential of IMPC." (PMID 39619442, 2024). "Interestingly, Allo/U15BCAR-NKT cells exhibited enhanced tumor cell killing in the presence of CD1d/αGC, indicating an iNKT TCR-directed targeting mechanism." (PMID 38584391, 2024). "Importantly, FACS analysis revealed a significant increase in CD19-B220+CD5+CD1d- cells in the livers of μMT mice at week 19 after tumor induction." (PMID 39611128, 2024). "iNKT cells have some unique beneficial biological properties which make them the ideal candidate for adoptive cell transfer to treat cancer such as the synergistic mechanism between the inherent anti-tumor activity against CD1d harboring cancer cells and the induction of host CD8+ T cell responses." (PMID 38993780, 2024). "It is worth noting that a significant proportion of primary MM tumor cells express both BCMA and CD1d, rendering them susceptible to both BCAR and iNKT TCR-mediated targeting, although CD1d expression levels may fluctuate with respect to MM disease stages." (PMID 38584391, 2024). "Rotolo and colleagues demonstrated that CAR iNKT cells against CD19 could exert better tumor control as compared to CAR T cells against CD19 through the synergistic interaction with CD1d and CD19 on lymphoma." (PMID 38993780, 2024). "Under high tumor load conditions and BCMA+CD1d+ tumor cells, Allo/U15BCAR-NKT cells still effectively suppressed tumor growth and achieved tumor clearance in a portion of the experimental mice (specifically, three out of five mice for Allo15BCAR-NKT cells and three out of six for U15BCAR-NKT cells)." (PMID 38584391, 2024). "Moreover, NKT cells play a crucial role in the antitumor immune response, exerting CD1d-dependent tumor cytotoxicity and interacting with various immune cells within the tumor microenvironment." (PMID 39119270, 2024). "Furthermore, iNKT cells derived from cancer patients release reduced levels of IFN-γ as they tend to exhibit a Th2 phenotype and CD1d expression can be downregulated in tumours, which abrogates the efficacy of the direct iNKT cell-mediated immune response." (PMID 37153585, 2023).
tumor (continued). "Moreover, the CAR19‐iNKT cells were found to eradicate the lymphomas in the brain, and in combination with all‐trans retinoic acid, which enhanced CD1D expression on tumor cells, the cytotoxicity of CAR19‐iNKT cells was further enhanced." (PMID 38045827, 2023). "However, the potential toxicity of CAR‐iNKT cells, especially the “off‐tumor, on‐target” effect of CD1d‐expressing cells still needs to be determined." (PMID 38045827, 2023). "Interestingly, and in contrast to observations using MM and AML tumor samples, the CD1d-Vδ2 hu-bsTCE only triggered minimal type 1 NKT cell activation and cytolytic activity in co-cultures with CLL cells." (PMID 36868236, 2023). "The CD1d+ tumors could be killed by NKT cells directly by recognizing CD1d-specific antigens on tumor cells; however, the clearance of CD1d− tumors is mediated by other immune cells like NK- and T-cells." (PMID 37158883, 2023). "In addition, other actions of NKT cells that induce tumor cell death include the stimulation of CD1d, activation of cell death receptors, and induction of perforin, granzyme B, and tumor necrosis factor-a-related apoptosis-inducing ligand (TRAIL) production." (PMID 37158883, 2023). "The frequencies of positively stained areas of the cell membrane and cytosol within the tumor tissue are as follows: β2M 8.2% (cell membrane) and 39.84% (cytosol); CD1d 6.72% (cell membrane) and 53.83% (cytosol); and CD1b 12.39% (cell membrane) and 55.18% (cytosol)." (PMID 37077920, 2023). "The frequency of type 1 NKT and Vγ9Vδ2-T cells in patient tumor samples was within the range of those reported in healthy human donors and, importantly, Vγ9Vδ2-T cells exposed to CD1d-Vδ2 bsTCE in such samples could be readily activated." (PMID 36868236, 2023). "The specificity of NKT cells can be increased by using α-GalCer/CD1d anti-tumor fusion proteins." (PMID 37158883, 2023). "Additionally, CD1d+ CD19+ lymphoma cells have been targeted by CAR-iNKT cells in a dual pronged attack which effectively localised to the tumour site, had potent anti-tumour activity, and significantly improved the long-term survival of treated mice." (PMID 37153585, 2023). "Notably, the MHC-I-like protein CD1d is constitutively expressed by tumor and dendritic cells (DCs), responsible for the presentation of non-peptide antigens, such as lipids and small metabolites, to natural killer T (NKT) cells." (PMID 37077920, 2023). "Therefore, we evaluated the abundance of intratumoral CD4+ Treg cells in CD1d−/− mice nourished with the control or WTMCGEP diet on day 28 after the tumor challenge." (PMID 37152373, 2023). "Thus, we measured the frequency of intratumoral MDSCs in CD1d−/− mice nourished with the control or WTMCGEP diet on day 28 after the tumor challenge." (PMID 37152373, 2023). "This implies that tumor metabolites present on tumor cell CD1d may be potential targets of iNKT-mediated immunotherapy against hematologic malignancies." (PMID 36830717, 2023). "LAVA-051 is a bispecific single domain antibody that directly engages CD1d and the Vδ2-T cell receptor chain of Vγ9Vδ2-T cells and additionally stabilizes the interaction between CD1d and type 1 natural killer T cells to mediate potent killing of CD1d-expressing tumor cells." (PMID 37501530, 2023). "Additionally, there is evidence that the altered metabolism of tumor cells results in the production of tumor antigens and enhanced CD1d antigen presentation." (PMID 37908366, 2023). "Moreover, in 7-day co-cultures of CD1d+ tumor cell lines and type 1 NKT and/or Vγ9Vδ2-T cells, CD1d-Vδ2 bsTCE mediated antitumor activity at a low E:T ratio of 1:10, which was variably accompanied by expansion of type 1 NKT and/or Vγ9Vδ2-T cells." (PMID 36868236, 2023). "In addition, recent study found that TAMs can promote tumor growth through producing IL-6, but accounting for majority of CD1d-expressing cells." (PMID 36845095, 2023).